TRAPPC6B (trafficking protein particle complex subunit 6B)
Description:
Component of a transport protein particle (TRAPP) complex that may function in specific stages of inter-organelle traffic. Specifically involved in the early development of neural circuitry, likely by controlling the frequency and amplitude of intracellular calcium transients implicated in the regulation of neuron differentiation and survival (Probable).
Synonyms: NEDMEBA; TPC6
Tractability: PROTAC: ubiquitination databases record sites on it; its protein half-life has been measured.
Gene: Protein-coding gene on chromosome 14 (39,147,811 to 39,170,532, reverse strand). Ensembl gene ENSG00000182400.
Subcellular location: Golgi apparatus, cis-Golgi network; Endoplasmic reticulum
Subcellular location (Human Protein Atlas): Endoplasmic reticulum
Pathways (Reactome):
Vesicle-mediated transport: COPII-mediated vesicle transport; RAB GEFs exchange GTP for GDP on RABs
Gene Ontology:
Molecular function: protein binding
Biological process: endoplasmic reticulum to Golgi vesicle-mediated transport; vesicle coating; Golgi vesicle transport
Cellular component: cis-Golgi network; cytoplasm; cytosol; trans-Golgi network; TRAPPII protein complex; endoplasmic reticulum; Golgi apparatus
Genetic constraint (gnomAD): Loss-of-function variants: 5 observed, 4.68 expected, observed/expected ratio (o/e) 1.07, 90% interval 0.54 to 1.84. That is too few expected variants to judge how well the gene tolerates losing a copy. Missense variants: 76 observed, 68.83 expected, observed/expected ratio (o/e) 1.1, 90% interval 0.92 to 1.34. Synonymous variants: 32 observed, 28.97 expected, observed/expected ratio (o/e) 1.1, 90% interval 0.83 to 1.48.
Gene-disease validity (ClinGen):
ClinGen rates the evidence that TRAPPC6B causes each of these diseases.
neurodevelopmental disorder with microcephaly, epilepsy, and brain atrophy (autosomal recessive): Definitive.
Homologues: Orthologues: chimpanzee TRAPPC6B (100% identical), dog TRAPPC6B (100% identical), guinea pig TRAPPC6B (100% identical), pig TRAPPC6B (100% identical), rat Trappc6b (99% identical), macaque TRAPPC6B (97% identical), mouse Trappc6b (97% identical), rabbit TRAPPC6B (85% identical), zebrafish trappc6b (84% identical), Drosophila melanogaster Trs33 (53% identical), Caenorhabditis elegans trpp-6 (46% identical). Paralogues in human: TRAPPC6A (56% identical).
Diseases named in the same sentence as TRAPPC6B in open-access papers:
TRAPPC6B is named in the same sentence as 6 diseases in open-access papers, as found by Europe PMC text mining. Sharing a sentence is not in itself a finding about the gene and the disease. The quoted sentences say what the papers report.
neurodevelopmental disorder (1 paper, 2018). A behavioral and cognitive disorder with onset during the developmental period that involves impaired or aberrant development of intellectual, motor, or social functions. "In summary, TRAPPC6A potentially adds to a growing list of TRAPP complex proteins (TRAPPC2, TRAPPC9, TRAPPC11), including the closely related TRAPPC6B, involved in neurodevelopmental disorders." (PMID 29391579, 2018).
TRAPPC6B also shares sentences with these, for which no sentence is quoted: microcephaly (3 papers); cancer (1); epilepsy (1); Lissencephaly (1); Periventricular heterotopia (1).